CBL (Cbl proto-oncogene)
Diseases named in the same sentence as CBL in open-access papers (continued):
Sharing a sentence is not in itself a finding about the gene and the disease.
cancer (continued). "There were more FLT3, FGFR1, and AKT1 mutations (p-value < 0.05) in nonhypermutated cancers, while there were more RET, CBL, and DDR2 mutations (p-value < 0.05) in hypermutated cancers." (PMID 34503126, 2021). "It seems plausible that E3-inactivated CBL could function in a similar manner to the MDS/MPN CBL mutants and cooperate with CIN85 to promote cancer progression." (PMID 33627783, 2021). "c-CBL is a key negative modulator of cell signal transduction, and its role has attracted widespread attention for the pathogenesis and regulation of human cancer." (PMID 39130630, 2024). "Interestingly, pCBL shows an inverse correlation with both CIN85 and CBL, suggesting that high levels of inactivated CBL could coordinate with CIN85 for cancer progression." (PMID 33627783, 2021). "Our study has the limitation that we were not able to evaluate some genetic alterations reported in CNS GCTs, such as NF1, CBL, and FGD6, which are not covered by the Oncomine Pan-Cancer Cell-Free Assay." (PMID 32868820, 2020). "Ubiquitin‐regulated signaling was represented with several relevant examples, most notably with the oncogene CBL and with the CUL1 and CUL4B homologs that are not yet in the Cancer Gene Census." (PMID 29572294, 2018).
infection (16 papers, 2010 to 2025). The state of being infected such as from the introduction of a foreign agent such as serum, vaccine, antigenic substance or organism. "Lentivirus vectors carrying CBL significantly promoted the expression of CBL protein at 72 h after infection (P < 0.01)." (PMID 34141730, 2021). "Compared with the control group, western blot and RT-PCR results showed that CBL shRNA 1 and shRNA 2 significantly inhibited CBL protein expression at 72 h after infection (P < 0.01)." (PMID 34141730, 2021). "In the present study, we demonstrated that the expression of the CaM, CML, CaMBP and CBL were all upregulated in ROC22, suggesting that these were more active than those in Yacheng05-179 after S. scitamineum infection." (PMID 27733120, 2016).
hematological malignancies (10 papers, 2012 to 2024). "Intriguingly, in comparison to the previous analysis, we observed 6 new non-synonymous SNVs linked to hematological disease, including variations in CBL (1 pt); DNMT3A (3 pts); FLT3 (1 pts), NQO1 (1 pt); NRAS (1 pts) and 2 frameshifts: CEBPA (1 pts) and NBN (1 pts)." (PMID 38612443, 2024). "CBL (11q23) codes for an E3 ubiquitin‐protein ligase that is involved in cell signaling and protein ubiquitination via receptor tyrosine kinases and mutations are associated with various hematological malignancies." (PMID 36504457, 2023). "At the pathological level, a number of features of the hematopoietic disease in VAV1-Cre-induced CBL/CBL-B DKO mice resemble those seen in JMML, as well as in previous models with CBL/CBL-B deletion or CBL RF mutation." (PMID 27449297, 2016). "Additionally, we characterized the predicted KMT2A-CBL protein structure in this case to reveal the underlying leukemogenic mechanisms and summarized reported cases of hematological malignancies with KMT2A::CBL fusion to investigate the correlation of gene rearrangements with clinical outcomes." (PMID 38643442, 2024).
immune disease (2 papers, 2022 to 2024). "CBL UbLOF variants may, therefore, contribute to immune disease in two ways: as strong risk modifiers in heterozygous individuals and as monogenic drivers of disease in people with somatic LOH." (PMID 39403923, 2024). "CBL (Cbl proto-oncogene B) proteins had multiple roles in regulating signal transduction, and their absence can mentor malignancy and immune disorders." (PMID 36230417, 2022).
overlap syndromes (2 papers, 2024 to 2025). "Although CBL’s role in MPN progression has been well-documented, emerging observations in overlap syndromes indicate that certain variants might unexpectedly limit proliferative signals through JAK2 destabilization." (PMID 40772034, 2025).
vascular disorder (2 papers, 2022). A general term used to describe any disease affecting blood vessels]. "Defective CBL function seems to promote myofibroblast migration into the endothelium and subsequent proliferation via signaling elicited by the PDGF receptor, potentially contributing to the vascular disorders." (PMID 36123612, 2022).
bacterial infections (1 paper, 2024). "We are currently assessing the impact of the CBL UbLOF variants in B cells, and this work will be dealt with in another manuscript focusing on the bacterial infections of P1–P5." (PMID 39403923, 2024).
metabolic disorder (1 paper, 2021). "An example includes the CBL variant NM_005188.3:c.1259G>A (p.R420Q), which is known to cause the early onset, severe metabolic disorder Noonan syndrome-like disorder [MIM: 613563]." (PMID 34906245, 2021).
CBL also shares sentences with these, for which no sentence is quoted: viral infection (5 papers); colorectal tumor (4); type 2 diabetes (4); acute lymphoblastic leukemia (3); cervical carcinoma (3); lung adenocarcinoma (3); multiple sclerosis (3); neurofibromatosis type 1 (3); atypical chronic myeloid leukemia (2); Bladder cancer (2); cardiofaciocutaneous syndrome (2); chronic lymphocytic leukaemia (2); chronic myeloid leukaemia (2); colitis (2); cryptorchidism (2); genetic diseases (2); Hepatic fibrosis (2); Jacobsen syndrome (2); Kaposi's sarcoma (2); leukocytosis (2); mastocytosis (2); neurofibromatosis (2); Parkinson disease (2); acute promyelocytic leukemia (1); adenoma (1); aortic stenosis (1); aortic valve stenosis (1); Arthritis (1); atherosclerosis (1); Bladder (1).
A further 67 diseases each share a sentence with CBL in 1 paper.